MACC1 (MET transcriptional regulator MACC1)
Diseases named in the same sentence as MACC1 in open-access papers (continued):
Sharing a sentence is not in itself a finding about the gene and the disease.
glioblastoma (14 papers, 2015 to 2024). The most malignant astrocytic tumor (WHO grade IV). "In glioblastoma, MACC1 promoted random motion in 2D, caused by a lower cortical stiffness and accumulation of protrusive actin near the protruding edge." (PMID 37051546, 2023). "Notably, in a previous study of ours, increased single cell velocities of glioblastoma cells were found upon increased MACC1 expression, which were associated with differential biomechanical properties and cytoskeletal organization." (PMID 35740524, 2022). "Addition of circulating MACC1 transcript levels to the existing prognostic workup may improve the accuracy of outcome prediction and help define more precise risk categories of glioblastoma patients." (PMID 31200581, 2019). "In glioblastoma stem cells the induction of autophagy limited tumor growth in vitro and in vivo, with a knockdown of MACC1 suppressing the phosphorylation of mTOR and further inducing the autophagy-associated genes LC3-II and beclin." (PMID 39580452, 2024). "This study identified that MACC1 overexpression increases the migratory speed, elasticity and reduces the contact area of glioblastoma cells." (PMID 39580452, 2024). "The current study aims to characterize the effect of MACC1 in glioblastoma on three hierarchical levels: multicellular, cellular and subcellular." (PMID 32503676, 2020). "We evaluated circulating plasma transcripts of metastasis-associated in colon cancer-1 (MACC1), a prognostic biomarker for solid cancer entities, for prediction of clinical outcome and therapy response in glioblastomas." (PMID 31200581, 2019). "Taking the hsa-mir-338 as an example, which ranked the first among all the miRNAs verified by dbDEMC or miR2Disease, recent research showed that the mir-338-3p inhibited malignant biological behaviors of Glioblastoma cells by targeting MACC1 gene." (PMID 29416734, 2018). "In conclusion, the results of the present study demonstrated that human glioblastomas exhibit increased expression of MACC1." (PMID 26043756, 2015). "Glioblastoma patients with low MACC1 expression receiving standard therapy survived longer compared to high MACC1 expressing patients receiving the same therapy (MACC1 low: 22.6 months vs MACC1 high: 8.1 months)." (PMID 39580452, 2024). "Arguments for MACC1 acting on cell–cell adhesions and cytoskeletal organization are supported by a study in HeLa cells showing lowered actin staining upon MACC1 silencing and by experiments on glioblastoma cells showing lower equilibrium cell–cell adhesion after MACC1 overexpression." (PMID 37051546, 2023). "Furthermore, in 2020, the impact of MACC1 on the cellular biomechanics of glioblastoma was studied." (PMID 39580452, 2024). "Metastasis-associated in colon cancer 1 (MACC1) is an established marker for metastasis and tumor cell migration in a multitude of tumor entities, including glioblastoma (GBM)." (PMID 32503676, 2020). "Yet, the intracellular organization of the vimentin cytoskeleton does not appear to be altered in glioblastoma cells upon MACC1 overexpression." (PMID 37051546, 2023). "In contrast, no MACC1-dependent change in the distribution of integrins α5 and β1 was found in glioblastoma cells." (PMID 37051546, 2023). "Similarly, adhesion to fibronectin and laminin of glioblastoma cells was not altered after MACC1 overexpression for short interaction times of 1 min." (PMID 37051546, 2023). "Moreover, MACC1 has also been established as a negative prognostic marker in genitourinary (kidney, bladder, ovarian, cervical and endometrial cancer), skin, breast, lung, head and neck cancer (head and neck, tongue, nasopharynx, salivary gland) as well as glioblastoma and retinoblastoma." (PMID 39580452, 2024).
adenoma (9 papers, 2013 to 2024). A neoplasm arising from the epithelium. "In order to test for potential difference in levels of circulating MACC1 transcripts in lesion-free-volunteers and adenoma patients, we measured MACC1 transcripts in normal (n = 45), hyperplastic (n = 15) and tubular adenoma (n = 33) patients’ blood." (PMID 27439755, 2016). "First transgenic MACC1 mice crossed with ApcMin mice demonstrated an accelerated adenoma-carcinoma sequence." (PMID 27439755, 2016). "We demonstrate significant correlations of MACC1 levels to early and late stage adenomas reflecting the potential use of this marker as a surrogate for tumor progression and metastasis risk assessment." (PMID 27439755, 2016). "When comparing the normals’ MACC1 transcripts to the group of tubular adenoma patients (n = 33; median 0.6045 MACC1 mRNA expression/percent calibrator), we also found significantly higher values for the adenoma patient group (p = 0.011)." (PMID 27439755, 2016). "In CRC and its prime metastasized organs liver and lung, MACC1 was found to be significantly upregulated when compared to mucosa and adenoma." (PMID 27462788, 2016). "MACC1 immunohistochemical staining was significantly different between normal vs. adenoma, and between normal vs. cancer cases, the p values for these differences were 0.004 and <0.001, respectively." (PMID 27439755, 2016). "In patient plasma, MACC1 transcripts in adenoma patients were significantly higher than in plasma from normal patients (p = 0.014)." (PMID 27439755, 2016). "MACC1 was found elevated at the crucial transition step from adenoma to carcinoma as well as in early stages of the disease allowing the early identification of high-risk patients." (PMID 27439755, 2016). "MACC1 induces the crucial step of carcinogenesis transition from adenoma to carcinoma in mice and human." (PMID 27462788, 2016). "Importantly, APCMin tumors of mice with additional MACC1 overexpression in the intestinal mucosa (villin-MACC1/APCMin) transformed these adenomas into invasive adenocarcinomas." (PMID 39580452, 2024). "For CRC it was shown that MACC1 occurs very early during the transition from adenoma to carcinoma." (PMID 32670264, 2020). "The expression of MACC1 is increased during the transition from adenomas to carcinomas." (PMID 32670264, 2020). "This might be due to the relatively small patient number in this group (p = 0.239), but might also reflect that levels of circulating MACC1 transcript might increase during the course from early to late (HPP to TA) adenomas." (PMID 27439755, 2016). "MACC1 transcripts were detected at a significantly higher level in all adenoma patients’ plasma (median 0.6036 MACC1 mRNA expression/percent calibrator) when compared to plasma of lesion-free volunteers (median 0.4315 MACC1 mRNA expression/percent calibrator; p = 0.014)." (PMID 27439755, 2016). "We then tested for MACC1 levels in different stages of adenoma development." (PMID 27439755, 2016). "We hypothesize that analyzing the MACC1 levels in liquid biopsies of African American adenoma patients might be beneficial for prognosis of the disease." (PMID 27439755, 2016). "Overexpressed MACC1 was contribute to the transformation of malignant degree and metastatic potential of CRC, primarily for adenoma transform into Tis further transform into invasive CRC." (PMID 33750337, 2021). "As for MACC1, DCLK1 increases in CRC during the transition from early-stage adenoma to more advanced dysplasia." (PMID 32756469, 2020). "Our tissue microarray analysis of normal, adenoma, and cancer samples revealed that MACC1 staining was not related to gender or age, nor was it related to anatomic location or mass size of adenoma or cancer lesions." (PMID 27439755, 2016). "For adenoma patients, such a MACC1-based blood test was never employed before with respect to diagnose adenoma cancer patients vs. lesion-free volunteers." (PMID 27439755, 2016).
adenoma (continued). "It is noteworthy that the adenoma cases were younger (p = 0.004) and their lesions smaller in size when compared to CRC (<0.001), but still MACC1 could be detected in these specimens at statistically significant levels compared to normal tissues." (PMID 27439755, 2016). "There was however no major difference in MACC1 expression between adenoma vs. cancer cases or tubular adenomas vs tubulovillous adenomas." (PMID 27439755, 2016). "In patient tissues, there was a statistically significant difference in MACC1 expression in normal vs. adenoma samples (p = 0.004) and normal vs. cancer samples (p < 0.001)." (PMID 27439755, 2016). "But although we also found MACC1 levels in adenomas there was not a statistically significant difference when compared to normal mucosa in the analyzed Caucasian cohort." (PMID 27439755, 2016). "Representative MACC1 stainings are shown for adenomas, non-metastasized and metastasized CRC." (PMID 27439755, 2016). "Adenoma vs CRC cases had similar MACC1 staining (ROC (95 % CI) 0.47 (0.40–0.55, not shown)." (PMID 27439755, 2016).
colon adenocarcinoma (9 papers, 2018 to 2024). "The purpose of the current study is to assess the expression of MACC1, CD44, Twist1, and KiSS-1 in the colonic adenocarcinoma (CAC) tissues of patients and their associations between pathological characteristics and prognosis of patients with CAC." (PMID 30021598, 2018). "In colon adenocarcinoma (COAD), using the cancer genome atlas (TCGA), a positive correlation between MACC1 mRNA and the intratumoral levels of natural killer (NK) cells, neutrophils, and macrophages, but not with T cells (incl." (PMID 39580452, 2024). "However, the associations of MACC1, CD44, Twist1, and KiSS-1 in colonic adenocarcinoma (CAC) invasion and metastasis remain unclear." (PMID 30021598, 2018). "Studies showed that overexpression of MACC1, CD44, Twist1, and LNM and TNM stages were independent predictors of prognosis in patients with colonic adenocarcinoma." (PMID 39695175, 2024). "The first study, which used bioinformatic analysis of colon adenocarcinoma (COAD) patients based on The Cancer Genome Atlas (TCGA), identified MACC1 as a positive regulator of the infiltration of natural killer (NK) cells, macrophages, and neutrophils." (PMID 38611008, 2024). "While SW480 cells have been established from a primary colon adenocarcinoma, lymph node metastasis from the same tumour gave rise to the cell line SW620, which endogenously expresses high levels of MACC1, with higher capacity to migrate and metastasise." (PMID 35597866, 2022).
glioma (8 papers, 2014 to 2022). A benign or malignant brain and spinal cord tumor that arises from glial cells (astrocytes, oligodendrocytes, ependymal cells). "MACC1 correlates with the staging of gliomas and is associated with their potential to form recurrences." (PMID 32503676, 2020). "The present study demonstrated that the expression levels of MACC1 were significantly correlated with the biological processes underlying glioma cell proliferation, invasion and metastasis." (PMID 26043756, 2015). "The present study aimed to investigate the effects of MACC1 expression silencing in glioma cells using RNA interference, in order to determine the underlying biological mechanisms of glioma progression, including proliferation, apoptosis, invasion and metastasis." (PMID 26043756, 2015). "However, the mechanisms underlying the role of MACC1 in glioma remain unclear, and the impact of MACC1 on proliferation, invasion, metastasis and survival has yet to be fully understood." (PMID 26043756, 2015). "MACC1 induces a more aggressive behavior of glioma and GBM cells by increasing proliferation and migration and decreasing apoptosis." (PMID 32503676, 2020). "Previous studies verified that silencing of MACC1 enhance the apoptosis and growth inhibitory rates of U251 glioma cells, and thereby increase their sensitivity to DDP chemotherapy." (PMID 28348518, 2017). "Compared with NBTs, the protein expression of MACC1 in glioma tissues was significantly increased, in addition, MACC1 expression was positively correlated with the increasing pathological grades of glioma." (PMID 28348518, 2017). "The silencing of MACC1 by shRNA significantly inhibited proliferation, migration and invasion, and promoted apoptosis in U251 human glioma cells." (PMID 26043756, 2015). "The expression levels of MACC1 were determined in various types of U251 glioma cells using western blot analyses." (PMID 26043756, 2015). "The relative intensity of MACC1 expression in the glioma cell lines was as follows: U251 (1.60±0.21), SHG44 (1.31±0.17), U373 (1.00±0.00), U87-MG (0.87±0.09), and A172 (0.83±0.10) (P<0.01)." (PMID 26043756, 2015). "Gliomas are the most common type of intracranial tumors, and recent studies have reported MACC1 to be involved in human glioma progression." (PMID 26043756, 2015). "In the present study, the expression levels of MACC1 were compared in various types of glioma cells." (PMID 26043756, 2015). "The present study aimed to investigate the effects of MACC1 on cell inhibition, proliferation, apoptosis, invasion, and metastasis in human U251 glioma cells, following transfection with MACC1-specific short hairpin RNA (shRNA) expression plasmids." (PMID 26043756, 2015). "In other cases, such as in rarely metastatic human glioma, MACC1 gene expression is more dramatically up-regulated in the tissues of higher malignancy, reflecting symptomatic deterioration of the disease." (PMID 24949951, 2014). "The protein expression levels of MACC1 were highest in U251 glioma cells." (PMID 26043756, 2015). "The expression levels of MACC1 were detected in various glioma cell lines by western blotting." (PMID 26043756, 2015). "Furthermore, MACC1 expression is increased in glioma, when compared to healthy brain tissue." (PMID 32503676, 2020). "Notably, the inhibition of MACC1 expression by shRNA may prove to be an effective genetic therapeutic strategy for glioma treatment." (PMID 26043756, 2015). "Therefore, MACC1 may serve as a promising novel therapeutic target in human glioma." (PMID 26043756, 2015). "While these cellular effects of MACC1 in glioma seem well established bio-mechanical studies were not yet performed." (PMID 32503676, 2020).
osteosarcoma (8 papers, 2017 to 2025). A usually aggressive malignant bone-forming mesenchymal neoplasm, predominantly affecting adolescents and young adults. "MACC1 promotes the development of osteosarcoma by regulating the HGF/c-Met pathway and microtubule stability." (PMID 40740230, 2025). "In osteosarcoma, MACC1 regulates the proliferation, colony formation, invasion ability, cell cycle distribution, apoptosis, and tumorigenicity of human osteosarcoma by altering the Akt signaling pathway." (PMID 36979146, 2023). "MACC1 can bind to the c-Met promoter and enhance the proliferation of osteosarcoma cells and endothelial cells through the HGF/c-Met signaling pathway." (PMID 35242498, 2022). "MACC1 can bind to the c-Met promoter and enhance the proliferation of osteosarcoma cells and vascular endothelial cells through the HGF/c-Met signaling pathway." (PMID 35242498, 2022). "Further, the causal involvement of MACC1 in angiogenesis was reported in several studies, e.g., for CRC, cervical, gastric, and hepatocellular cancer, for cholangiocarcinoma, brain microvascular endothelial cells, osteosarcoma, and oral squamous cell carcinoma." (PMID 35406521, 2022).
nasopharyngeal carcinoma (7 papers, 2013 to 2022). A carcinoma arising from the nasopharyngeal epithelium. "Association of MACC1 expression with the clinicopathological features of nasopharyngeal carcinoma patients." (PMID 23573286, 2013). "Our recent study shows that MACC1 down-regulation inhibits proliferation and tumorigenicity of nasopharyngeal carcinoma cells." (PMID 25003996, 2014). "Our recent study has reported that MACC1 down-regulation inhibits proliferation and tumourigenicity of nasopharyngeal carcinoma cells through Akt/beta-catenin signaling pathway." (PMID 25003996, 2014). "The relationship between p-Akt expression and MACC1, β-catenin, and Met expression in nasopharyngeal carcinoma tissue." (PMID 23573286, 2013). "The present study was aimed at investigating the expression of metastasis-associated in colon cancer 1 (MACC1) in nasopharyngeal carcinoma (NPC), its relationship with β-catenin, Met expression and the clinicopathological features of NPC, and its roles in carcinogenesis of NPC." (PMID 23573286, 2013).
liver cancer (6 papers, 2011 to 2024). An epithelial or non-epithelial malignant neoplasm that arises from the liver. "Our results showed that SS-b2 had an obvious effect on MACC1/c-Met/Akt pathway–associated molecular expression in HepG2 liver cancer cells and H22 sarcoma xenograft mice." (PMID 39544485, 2024). "We investigated the inhibition of tumour proliferation by SS-b2 and the underlying molecular mechanisms, including the MACC1/p-c-Met/p-Akt pathway expression in HepG2 liver cancer cells and H22 tumour-bearing mice." (PMID 39544485, 2024). "In conclusion, our study demonstrated that the antitumour effects of SS-b2 on liver cancer cells occur via its effect on the MACC1/c-Met/Akt pathway." (PMID 39544485, 2024). "The mRNA expression levels of MACC1 and c-Met in HepG2 liver cancer cells treated with different doses of SS-b2 (40 or 80 mg/L) for 24 h were significantly decreased relative to the control group (p < 0.05 and p < 0.01, respectively)." (PMID 39544485, 2024). "Our previous research identified the pivotal role of SS-b2 in the suppression of MACC1 in hepatocarcinogenesis and its antitumour efficacy in liver cancer." (PMID 39544485, 2024). "This study is the first to demonstrate that SS-b2 is a potent inhibitor of MACC1 and can target the c-Met/Akt signalling pathway in HepG2 liver cancer cells and H22 sarcoma xenograft mice." (PMID 39544485, 2024). "MACC1 is also highly expressed in liver cancer and is a prognostic indicator in patients with liver cancer." (PMID 39544485, 2024). "Our findings suggest that SS-b2 is a promising novel candidate for the prevention and therapy of liver cancer by inhibiting the expression of MACC1." (PMID 39544485, 2024). "The consistency of MACC1 mRNA levels in colorectal and liver cancer makes it a strong candidate marker for NPC prognosis." (PMID 33854976, 2021). "Upregulation of MACC1 has been found in colorectal cancer, gastric cancer, liver cancer, lung cancer, non-small cell lung cancer, cervical cancer, ovarian cancer, NPC, and malignant gliomas." (PMID 33854976, 2021). "Similar results were obtained from the same batch of cell lines using Q-PCR, which indicated high MACC1 mRNA expression in liver cancer cell lines, while there was low expression in normal liver cells." (PMID 21955323, 2011). "Additionally, the suppression of MACC1 activation by SS-b2 resulted in a reduction in the viability and proliferation of HepG2 liver cancer cells, and this reduction was comparable to that by doxorubicin (DOX)." (PMID 39544485, 2024). "Clinicopathological characteristics of clinical samples and expression of MACC1 in liver cancer." (PMID 23717574, 2013). "Correlation between MACC1 expression and clinicopathologic characteristics of liver cancer patient." (PMID 23717574, 2013). "Furthermore, based on c-MET contributes to the aggressiveness of HCC, this correlation might further indicate that MACC1 enhances the invasiveness of liver cancer cells." (PMID 21955323, 2011). "Animal experiments showed that SS-b2 significantly decreased the levels of MACC1, p-c-MET and p-Akt in tumour tissue transplanted with H22 liver cancer cells in mice, while it increased the expression of p-BAD." (PMID 39544485, 2024).